RNU6-843P (RNA, U6 small nuclear 843, pseudogene)
Gene: Small nuclear RNA gene on chromosome 2 (12,411,398 to 12,411,501, reverse strand). Ensembl gene ENSG00000207183.
Homologues: Orthologues: chimpanzee U6 (100% identical), macaque U6 (94% identical), mouse Gm22302 (90% identical), rat U6 (90% identical), rat U6 (89% identical), guinea pig U6 (88% identical), guinea pig U6 (83% identical). Paralogues in human: RNU6-1060P (91% identical), RNU6-15P (91% identical), RNU6-19P (91% identical), RNU6-80P (91% identical), RNU6-1024P (90% identical), RNU6-1181P (90% identical), RNU6-12P (90% identical), RNU6-13P (90% identical), RNU6-21P (90% identical), RNU6-31P (90% identical), RNU6-32P (90% identical), RNU6-41P (90% identical), and 1286 more.